TPO (thyroid peroxidase)
Diseases named in the same sentence as TPO in open-access papers (continued):
Sharing a sentence is not in itself a finding about the gene and the disease.
aplastic anemia (17 papers, 2017 to 2026). Anemia resulting from bone marrow failure (aplastic or hypoplastic bone marrow). "Thrombopoietin receptor agonist (TPO-RA) is effective for aplastic anemia (AA) and idiopathic thrombocytopenic purpura (ITP)." (PMID 38800784, 2024). "Thrombopoietin receptor agonists (TPO-RA) are currently indicated for the treatment of chronic immune thrombocytopenia and relapsed refractory aplastic anemia." (PMID 35455416, 2022). "Accordingly, therapy with thrombopoietin receptor agonists (TPO-RA), labeled for immune thrombocytopenia and aplastic anemia, has shown some efficacy in thrombocytopenic MDS patients." (PMID 35392224, 2022). "TPO-RAs have been found to improve trilineage hematopoiesis in aplastic anemia patients despite the presence of high levels of endogenous thrombopoietin, which suggests that analogs may exert this effect using alternative anti-inflammatory mechanisms." (PMID 39274330, 2024). "Short-term efficacy and safety of afatrombopag conversion therapy in patients with aplastic anemia(AA)who were previously ineffectively treated with intense immunosuppressive therapy(IST)combined with TPO receptor Agonist(TPO-RA)or who were unable to tolerate the side effects of TPO-RA." (PMID 36709183, 2022). "Therefore, TPO-RA also played a critical role in severe aplastic anemia." (PMID 36873638, 2023). "The current standard first-line therapy for aplastic anemia (AA) consists of antithymocyte globulin (ATG), cyclosporine, and thrombopoietin receptor agonists (TPO-RAs)." (PMID 41044163, 2025). "TPO-RAs, like eltrombopag, romiplostim, and, more recently, avatrombopag, are indicated to restore platelet counts in ITP and severe aplastic anemia and have also been successfully used after allogeneic stem cell transplantation or chemotherapy." (PMID 39274330, 2024). "Several TPO-R agonists demonstrate similar hematopoietic activities in aplastic anemia, including TPO peptide mimetic romiplostim, which does not inhibit TET2." (PMID 35085104, 2022). "In conclusion, IL-11 stimulates HSC proliferation and increases TPO expression in vitro, which may explain the stimulating role of IL-11 treatment on HSC transplantation in a mouse model of aplastic anemia." (PMID 29217821, 2017). "In these patients with LR-MDS, refractory cytopenia, and hypoplastic bone marrow (<25% cellularity), we consider immune-suppressive treatment with anti-thymocyte globulin (ATG), cyclosporine with or without thrombopoietin-receptor agonist (TPO-RA), analogous to the treatment of aplastic anemia." (PMID 36517487, 2022). "Eltrombopag (EPAG), an oral thrombopoietin receptor agonist (TPO-RA), has been proven to improve the hematologic response without increasing toxic effects as a first-line therapy combined with standard immunosuppressive treatment (IST) in adults with severe aplastic anemia (SAA)." (PMID 36704148, 2022). "Our case report underscores the feasibility of this approach in non-VSAA patients with milder aplastic anemia, suggesting that ATG-free regimens combined with TPO-RAs may serve as viable alternatives for SAA patients." (PMID 40927718, 2025).
immune thrombocytopenia (16 papers, 2016 to 2025). "In recent years, significant advances have been made in the treatment of immune thrombocytopenia (ITP) with the development of thrombopoietin receptor agonists (TPO-RAs)." (PMID 40098741, 2025). "Avatrombopag, a thrombopoietin receptor agonist (TPO-RA), is used for immune thrombocytopenia (ITP) but confers thrombotic risks." (PMID 40936593, 2025). "Thrombopoietin receptor agonists (TPO-RAs) are commonly used as second-line treatments for immune thrombocytopenia (ITP)." (PMID 40573298, 2025). "We report two cases of immune thrombocytopenia occurring 1–2 weeks after receiving a first vaccination with the AstraZeneca COVID-19 vaccine, with both showing a good response to TPO-RA therapy." (PMID 39449300, 2024). "Thrombopoietin receptor agonists (TPO-RA) such as eltrombopag, romiplostim, and avatrombopag have shown efficacy in treating immune thrombocytopenia." (PMID 37335880, 2023). "We use randomized controlled clinical trials of TPO-RAs for treatment of immune thrombocytopenia in adults." (PMID 34393785, 2021). "In absence of direct comparison randomized controlled trials (RCTs), indirect comparison was conducted to evaluate the efficacy and safety of thrombopoietin-receptor agonists (TPO-RAs) in treatment of adult immune thrombocytopenia (ITP)." (PMID 29856837, 2018). "Romiplostim, a thrombopoietin-receptor agonist (TPO-ra), is a highly effective option in primary immune thrombocytopenia (ITP), with 80-90% of patients achieving platelet responses after few weeks of treatment." (PMID 28695025, 2017). "Thrombopoietin receptor agonists (TPO-RA), such as eltrombopag, romiplostim, and avatrombopag, have shown efficacy in treating immune thrombocytopenia; however, their efficacy in improving platelet counts due to HER2-targeted antibody-drug conjugate therapy remains unknown." (PMID 37335880, 2023). "She had previously been diagnosed with immune thrombocytopenia (ITP) and treated with steroids, intravenous immunoglobulin (IVIG), and thrombopoietin receptor agonists (TPO-RA)." (PMID 40689043, 2025).
anemia (15 papers, 2018 to 2025). A reduction in the number of red blood cells, the amount of hemoglobin, and/or the volume of packed red blood cells. "Treatments that could be required for managing isolated ITP and that are associated with an increased risk of thrombosis such as IVIg and TPO-RA should be used with caution in ES as ES-anaemia probably increases the risk of thrombosis, as observed in isolated AIHA." (PMID 33260979, 2020). "FT4: ↓ in IDTT4: ↔TSH: ↑ in IDTPO-Ab: ↑ in ID anemia* In mothers with ID, overt and subclinical hypothyroidism and TPO-Ab positivity was ↑." (PMID 39944206, 2025). "Another deleterious effect of anemia is thyroid hormone dysfunction following reduction of the activity of thyroid peroxidase (TPO) enzyme." (PMID 30402283, 2018). "In our patient, low ferritin (15 ng/mL) and mild anemia may have contributed to persistent fatigue and elevated anti-TPO antibody levels." (PMID 40978905, 2025). "Some studies have noted that anemia can weaken thyroid function by reducing TPO activity." (PMID 32351449, 2020). "One death was complicated by the addition of TPO-RA therapy and a contraindication to anticoagulation due to a recent cerebral bleed, while the other had active pancreatitis, a genetic thrombophilia, and a severe anemia of unclear etiology with a contraindication to anticoagulation." (PMID 38999278, 2024). "Anti-TG, anti-TPO, TSH, anemia, and ruminant exposure were higer in HT patients than in the HCs (p < 0.05)." (PMID 36204645, 2022). "The established PK/PD model could help to facilitate the clinical development of different strategies involving combinations of other ESAs and TPO-Ras and can be used to select starting doses in the treatment of CKD anemia." (PMID 36839666, 2023).
Insulin resistance (15 papers, 2014 to 2026). Increased resistance towards insulin, that is, diminished effectiveness of insulin in reducing blood glucose levels. "Serum CART levels showed positive correlations with body mass index and insulin resistance indices, while inverse correlations were observed with thyrotropin receptor antibody and anti-thyroid peroxidase antibody levels." (PMID 41828644, 2026). "When comparing clinical, hormonal, and biochemical values, the median levels of TSH, anti-TPO, anti-Tg, glucose, triglycerides, insulin, and homeostatic model assessment for insulin resistance score were significantly higher in the HT group (p < 0.05 for all)." (PMID 40337564, 2025). "Previous studies have reported that anti-TPO positivity precedes insulin resistance by approximately one year, highlighting its potential utility as an early warning marker for metabolic and reproductive compromise." (PMID 41303060, 2025). "We propose one-time laboratory diagnostics taking into account the lipid profile, insulin resistance, anti-thyroid-peroxidase, and total IgE in both males and females with unexplained subfertility." (PMID 37763034, 2023). "Given the established link between insulin resistance and ovarian dysfunction, especially in PCOS, anti-TPO screening may offer an upstream approach to risk stratification." (PMID 41303060, 2025). "In addition, higher values of anti TPO antibody (thyroid autoantibody) were found in the GDM group which aids in insulin resistance." (PMID 37581158, 2023). "HOMA-IR: homeostatic model assessment-insulin resistance, TSH: thyroid-stimulating hormone, TPO: thyroid peroxidase, Tg: thyroglobulin." (PMID 38094874, 2023). "Anti-TPO: anti thyroid peroxidase, HOMA-IR: homeostatic model assessment for insulin resistance." (PMID 39759697, 2024). "We evaluated the patients' fasting plasma glucose, insulin, homeostasis model assessment of insulin resistance index (HOMA-IR), thyroid-stimulating hormone (TSH), free thyroxine (FT4), antithyroperoxidase antibodies (TPO-Ab), antithyroglobulin antibodies (Tg-Ab), and thyroid ultrasound." (PMID 29412382, 2017).
thyroid tumor (15 papers, 2001 to 2025). A benign or malignant neoplasm affecting the thyroid gland. "In this study, we described six novel independent murine PTC cell lines that were derived from BrafV600E+/−/Pten+/−/TPO-Cre mouse thyroid tumors." (PMID 36765847, 2023). "Among the identified hub genes, AEBP1, CD34, COL12A1, ITGA2B, THBS2, and TPO exhibit lower expression levels in thyroid tumors." (PMID 37795451, 2023). "The biological reason for a typical TPO expression in thyroid tumors is obscure, but the progressive reduction of TPO levels together with an increase in cell density suggests that it is linked with the proliferation process." (PMID 35571253, 2022). "In addition, PFOS and PFOA reduce thyroperoxidase (TPO) activity in tumor thyroid cells lines and PFOS was suggested to act as a thyroid hormone receptor (THR) agonist in GH3 cells as found by using THRα and THRβ-mediated luciferase reporter assay." (PMID 33542707, 2020). "TPO-Cre/LSL-BrafV600E transgenic mice were studied to assess the effects of digoxin treatment on the proliferation and differentiation of BrafV600E-driven thyroid tumors." (PMID 33534128, 2021).
Thrombocytosis (14 papers, 2013 to 2025). Increased numbers of platelets in the peripheral blood. "In ovarian cancer patients, the level of TPO is linked to thrombocytosis and to advanced disease and poor survival." (PMID 26622942, 2015). "Corticosteroids, TPO-RA, and new therapies such as rituximab can be used effectively, although they require close monitoring to minimize the risk of complications such as thrombocytosis, infections, or hypertension." (PMID 39597882, 2024). "The concurrent use of IVIG and a TPO-RA in the perisplenectomy period may also increase thrombocytosis risk since the half-life of IVIG is prolonged in excess of two weeks." (PMID 27812394, 2016). "However, given the known thrombotic complications with TPO-RAs, one must also consider the postsplenectomy risk of thrombocytosis and thrombotic events, which typically warrant thrombosis prophylaxis and antiplatelet therapy." (PMID 27812394, 2016). "When encountering patients with thrombocytosis (Sustained platelet count > 450x109/L), excluding secondary reasons such as post-splenectomy, malignancy, and connective tissue diseases, Type 2 and TPO mutation screenings should be performed if the patients have familial history." (PMID 23351976, 2013). "While there is some data that TPO-RAs can be safe in the days leading up to splenectomy to achieve platelet numbers to minimize surgical risk, there is an inherent risk for postsplenectomy thrombocytosis that may be augmented by recent TPO-RA therapy." (PMID 27812394, 2016). "She demonstrated marked cyclic platelet oscillations despite receiving corticosteroids, IVIG, rituximab, splenectomy, and TPO-RAs, and while on eltrombopag, she continued to have extreme rebound thrombocytosis." (PMID 41293611, 2025). "In conclusion, there is minimal data to truly assess the temporal relationship between TPO-RA administration and extreme thrombocytosis after splenectomy in patients with ITP." (PMID 27812394, 2016). "Thrombocytosis has been reported after splenectomy in patients treated with TPO-RA preoperatively, with one prior case requiring plateletpheresis for symptomatic thrombocytosis." (PMID 27812394, 2016). "We present a case report and review of the literature pertaining to this complication and provide recommendations for preventing postsplenectomy thrombocytosis in ITP patients on TPO-RAs." (PMID 27812394, 2016). "It has been hypothesized that, in inflammatory states and malignant diseases, thrombocytosis might be mediated through an IL-6–induced increase in TPO levels." (PMID 25025065, 2014). "One patient had an emergency room visit due to iatrogenic thrombocytosis from treatment (platelet transfusion, IVIG, steroids, TPO-RA, and vincristine during hospitalization)." (PMID 36146522, 2022). "Eltrombopag and romiplostim are two TPO agonists ever used for CIT, but there are only a few small-scale studies about the efficacy in the recent years, and possible thrombocytosis after the medication is of concern." (PMID 30174705, 2018). "In terms of safety, except for one case of neonatal thrombocytosis, no maternal thrombotic events occurred, and no fetal or neonatal complications related to TPO-RA were observed." (PMID 40041460, 2025). "Reports describe patients who failed to maintain stable platelet counts despite prolonged TPO-RA therapy, and some even developed thromboembolic events due to rebound thrombocytosis." (PMID 41293611, 2025). "HFD-treated 3 × Tg mice also exhibited increased platelet production (thrombocytosis) and MPV that could be partially attributed to elevated IL-6 and TPO, which induce MK differentiation into platelets." (PMID 34454596, 2021).
urticaria (14 papers, 2011 to 2025). A vascular reaction of the skin characterized by erythema and wheal formation due to localized increase of vascular permeability. "Elevation of anti-TPO IgE during exacerbation periods supports an association between this autoantibody and the pathogenesis of urticaria." (PMID 31886301, 2019). "Elevation of anti-TPO IgE during exacerbations supports a possible association between this autoantibody and the pathogenesis of urticaria which should be explored in more detail." (PMID 31886301, 2019). "The answer to this question may also help to clarify whether the presence of anti-TPO IgE in healthy subjects represents a risk for the development of urticaria." (PMID 31886301, 2019). "These IgE-anti-TPO autoantibodies, when bound and activated on the surfaceof mast cells, could cause ‘autoallergic’ mast cell degranulation, a novelpathogenic pathway of urticaria induction." (PMID 21532759, 2011). "In patients with CSU, the increased prevalence of elevated anti-TPO antibodies compared to the general population suggests a potential link between thyroid dysfunction and the development of urticaria." (PMID 40075855, 2025). "Forty-three patients had positive anti-TPO IgE during the clinical control period (UAS 0) or during at least 1 urticaria exacerbation (UAS ≥ 3)." (PMID 31886301, 2019). "Anti-TPO IgE levels were measured during the clinical control period (Urticaria Activity Score, 0 point) and exacerbation period (≥3 points) in 100 CSU patients." (PMID 31886301, 2019). "In other words: IgG-anti-TPO-positive patients are more likely to expresspotentially urticaria-inducing IgE-anti-TPO." (PMID 21532759, 2011). "In addition, role of 2 commonly evaluated markers in urticaria, that is, total serum IgE and anti-TPO antibody was also assessed in predicting disease severity and response to antihistamine therapy." (PMID 38482455, 2024). "Together, these results suggest a role for anti-TPO IgE in urticaria." (PMID 31886301, 2019). "As it has been shown that in chronic cases of urticaria a specific set of IgE autoantibodies directed against thyroid peroxidase may constitute a novel pathogenetic mechanism, this may be serious for chronic NSAID users." (PMID 28573063, 2017). "Current international urticaria guidelines recommend the following basic tests for all patients with CSU: differential blood count and CRP (to help rule out an underlying systemic disease) and total IgE and anti-thyroid peroxidase levels (which are important for predicting treatment response)." (PMID 39654029, 2024). "Moreover, basophil activation by anti-TPO IgE suggests that this immunoglobulin could participate in exacerbations of urticaria, and in vivo results show that anti-TPO IgE can induce wheals in the skin of CSU patients." (PMID 31886301, 2019). "However, we made corrections for analysis with multiple variables, and the association between negative anti-TPO and inducible urticarias (IUs) persists, which suggested a real association." (PMID 31886301, 2019). "Data including patent’s demographics, comorbidities, urticaria activity score (UAS7), urticaria control test (UCT), laboratory findings including Anti-TPO, treatment regimens and treatment response were collected." (PMID 40745660, 2025). "We used our prospective registry of 93 patients, which included CSU disease duration, the onset of OMA treatment, Urticaria Activity Score (UAS7) during follow-up, co-morbidities, serum IgE levels and the presence of anti-TPO antibodies." (PMID 39416263, 2024). "The association of negative anti-TPO IgE group with inducible urticaria could be for different factors; as the calculation of the sample and the analysis of the outcomes were done by evaluating the presence of the TPO, the associations observed in the group without TPO can be a statistical artifact." (PMID 31886301, 2019).
urticaria (continued). "In the 43 patients with anti-TPO IgE elevation during the exacerbation of urticaria, we measured the levels of Der f, Blo t, and Can f; none of them had a significant increase in ration at baseline levels (p 0.18, 0.24, 0.12, respectively)." (PMID 31886301, 2019). "We recorded production and elevation of anti-TPO IgE levels during skin exacerbations in patients with CSU; these results support the hypothesis that there is a relationship between anti-TPO IgE and urticaria." (PMID 31886301, 2019). "Patients with anti-TPO IgE (during control or exacerbation periods) had a significantly higher frequency of atopy, total IgE levels, and asthma; patients without anti-TPO IgE (during the control and exacerbation periods) had a higher frequency of inducible urticaria." (PMID 31886301, 2019). "Furthermore, other clinical and laboratory parameters—including the duration of urticaria, positivity rates in ASST, incidence of combined angioedema, total IgE levels, IgG anti-TPO levels, eosinopenia, and basopenia—did not reveal significant differences between the groups." (PMID 41218021, 2025).
rheumatoid arthritis (13 papers, 2011 to 2025). A chronic, systemic autoimmune disorder characterized by inflammation in the synovial membranes and articular surfaces. "A previous study with three years follow-up of rheumatoid arthritis patients reported a larger carotid intima-media thickness (CIMT) progression in patients TPO-Ab positive than in those TPO-Ab negative." (PMID 35159980, 2022).